MFAP1 (microfibril associated protein 1)
Description:
Involved in pre-mRNA splicing as a component of the spliceosome.
Synonyms: AMP
Tractability: Small molecule: a structure with a bound ligand is known. PROTAC: UniProt records ubiquitination sites on it; ubiquitination databases record sites on it; its protein half-life has been measured.
Gene: Protein-coding gene on chromosome 15 (43,804,492 to 43,824,733, reverse strand). Ensembl gene ENSG00000140259.
Subcellular location: Nucleus
Subcellular location (Human Protein Atlas): Nucleoplasm; Centrosome
Pathways (Reactome):
Metabolism of RNA: mRNA Splicing - Major Pathway
Gene Ontology:
Molecular function: protein binding; RNA binding
Biological process: mRNA splicing, via spliceosome
Cellular component: microfibril; nucleoplasm; nucleus; U2-type precatalytic spliceosome; non-collagenous component of interstitial matrix; U2-type spliceosomal complex
Genetic constraint (gnomAD): Loss-of-function variants: 18 observed, 64.79 expected, observed/expected ratio (o/e) 0.28, 90% interval 0.19 to 0.41. The upper end of that interval is the gene's LOEUF score, 0.41, which puts it in group 1 of 6, group 1 being the genes least tolerant of losing a copy. Missense variants: 355 observed, 582.72 expected, observed/expected ratio (o/e) 0.61, 90% interval 0.56 to 0.67. Synonymous variants: 175 observed, 189.36 expected, observed/expected ratio (o/e) 0.92, 90% interval 0.82 to 1.05.
Homologues: Orthologues: chimpanzee MFAP1 (100% identical), rabbit MFAP1 (100% identical), macaque MFAP1 (99% identical), pig MFAP1 (99% identical), mouse Mfap1a (99% identical), mouse Mfap1b (99% identical), rat Mfap1a (99% identical), rat Mfap1al1 (99% identical), guinea pig MFAP1 (98% identical), tropical clawed frog mfap1 (89% identical), dog MFAP1 (83% identical), zebrafish mfap1 (82% identical), and 1 more.
Diseases named in the same sentence as MFAP1 in open-access papers:
MFAP1 is named in the same sentence as 9 diseases in open-access papers, as found by Europe PMC text mining. Sharing a sentence is not in itself a finding about the gene and the disease. The quoted sentences say what the papers report.
Marfan syndrome (3 papers, 2010 to 2014). A disorder of the connective tissue. "All these genes are highly expressed in cartilage and mutations in these genes can cause chondrodysplasia (EVC, EVC2), Marfan syndrome (MFAP1) or restless legs syndrome (PTPRD)." (PMID 24802516, 2014). "The Saf3 human ortholog was mistakenly implicated in Marfan syndrome and named microfibrillin-associated protein-1 (MFAP1)." (PMID 21386897, 2011). "MFAP1 is located near FBN1 and mutations in both genes are causal for Marfan syndrome." (PMID 20949002, 2010).
Obesity (1 paper, 2026). Accumulation of substantial excess body fat. "CONCLUSIONS: This study supports obesity as a genetic risk factor for LUSC and highlights MFAP1 as a potential shared target at the interface of adiposity and squamous lung carcinogenesis." (PMID 41820721, 2026).
viral infection (1 paper, 2024). "UBL5 (ubiquitin-like protein 5), SNIP1 (Smad Nuclear Interacting Protein 1), TWISTNB (RNA Polymerase I Subunit F) and MFAP1 (Microfibril Associated Protein 1) have not been reported in affecting viral infection before." (PMID 39715740, 2024).
cancer (3 papers, 2021 to 2025). A tumor composed of atypical neoplastic, often pleomorphic cells that invade other tissues. "Further validation in four independent cohorts showed that KEAP1, SRI, MFAP1, MFAP2, INCENP, and KIF21B were consistently upregulated in cancer tissues, while MYOZ3, DST, and TIAM1 were consistently downregulated." (PMID 40228435, 2025). "MFAP1, MFAP2 and MFAP3 were up-regulated in both EAC and ESCC, while MFAP4 and MFAP5 were down-regulated in cancer tissues, indicating that MFAP2 might play crucial role in ESCC." (PMID 40657371, 2025).
MFAP1 also shares sentences with these, for which no sentence is quoted: chondrodysplasia (1 paper); esophageal cancer (1); lung squamous cell carcinoma (1); renal dysfunction (1); restless legs syndrome (1).